DUX4L5 (double homeobox 4 like 5 (pseudogene))
Description:
May be involved in transcriptional regulation.
Gene: Unprocessed pseudogene on chromosome 4 (190,077,818 to 190,079,092, forward strand). Ensembl gene ENSG00000280799.
Subcellular location: Nucleus